ENSG00000206853
Synonyms: LOC124900267
Gene: Small nucleolar RNA gene on chromosome 8 (59,137,372 to 59,137,502, reverse strand). Ensembl gene ENSG00000206853.
Gene Ontology:
Biological process: RNA processing
Cellular component: nucleolus
Homologues: Paralogues in human: SNORA51 (79% identical).